MSRB3 (methionine sulfoxide reductase B3)
Description:
Catalyzes the reduction of free and protein-bound methionine sulfoxide to methionine. Isoform 2 is essential for hearing.
Synonyms: FLJ36866; DKFZp686C1178; DFNB74
Tractability: Antibody: UniProt predicts a signal peptide or a membrane-spanning region.
Target class: Enzyme; Oxidoreductase
Gene: Protein-coding gene on chromosome 12 (65,278,643 to 65,491,430, forward strand). Ensembl gene ENSG00000174099.
Subcellular location: Endoplasmic reticulum (Isoform 1); Mitochondrion (Isoform 2)
Pathways (Reactome):
Metabolism of proteins: Protein repair
Gene Ontology:
Molecular function: peptide-methionine (R)-S-oxide reductase activity; protein binding; zinc ion binding; L-methionine (R)-S-oxide reductase activity; oxidoreductase activity, acting on a sulfur group of donors, disulfide as acceptor
Biological process: protein repair; response to oxidative stress
Cellular component: endoplasmic reticulum; mitochondrion; cytosol
Genetic constraint (gnomAD): Loss-of-function variants: 7 observed, 13.68 expected, observed/expected ratio (o/e) 0.51, 90% interval 0.29 to 0.96. The upper end of that interval is the gene's LOEUF score, 0.96, which puts it in group 4 of 6, group 1 being the genes least tolerant of losing a copy. Missense variants: 167 observed, 195.51 expected, observed/expected ratio (o/e) 0.85, 90% interval 0.75 to 0.97. Synonymous variants: 64 observed, 79.33 expected, observed/expected ratio (o/e) 0.81, 90% interval 0.66 to 0.99.
Gene-disease validity (ClinGen):
ClinGen rates the evidence that MSRB3 causes each of these diseases.
nonsyndromic genetic hearing loss (autosomal recessive): Definitive. A disease characterized by hearing loss that is not part of a larger syndrome.
Homologues: Orthologues: guinea pig MSRB3 (94% identical), mouse Msrb3 (92% identical), chimpanzee MSRB3 (90% identical), macaque MSRB3 (87% identical), pig MSRB3 (81% identical), dog MSRB3 (78% identical), rat Msrb3 (75% identical), tropical clawed frog MSRB3 (64% identical), zebrafish msrb3 (59% identical), Drosophila melanogaster SelR (44% identical), Caenorhabditis elegans F44E2.6 (32% identical). Paralogues in human: MSRB2 (37% identical), MSRB1 (22% identical), MSRA (19% identical).
Diseases named in the same sentence as MSRB3 in open-access papers:
MSRB3 is named in the same sentence as 25 diseases in open-access papers, as found by Europe PMC text mining. Sharing a sentence is not in itself a finding about the gene and the disease. The quoted sentences say what the papers report.
deafness (12 papers, 2014 to 2025). An inherited or acquired condition characterized by the complete loss of the ability to hear from one or both ears. "The Msrb3-deficient mice showed profound deafness by postnatal day 16, which was accompanied by morphological abnormalities including altered stereocilia bundle shape and cuticular plate degeneration, followed by hair cell apoptotic death." (PMID 40827380, 2025). "Loss-of-function of MSRB3, which encodes a methionine sulfoxide reductase, has been associated with human deafness." (PMID 36525587, 2023). "Human MsrB3 mutations are linked to non-syndromic deafness, and MsrB3 knockout correspondingly produces deafness in mice." (PMID 32517586, 2020). "In humans, mutations of the MSRB3 gene are usually linked to autosomal recessive pre-lingual individual deafness." (PMID 30231496, 2018). "MSRB3-catalyzed reduction of methionine sulfoxides to methionine is essential for hearing and a non-synonymous substitution in this gene causes deafness and expression of MSRB3 in the inner ear is localized in the auditory and vestibular sensory epithelia." (PMID 26100605, 2015). "A nonsynonymous mutation has been identified that causes deafness in a human family and the expression of MSRB3 in the inner ear is essential for hearing." (PMID 26100605, 2015). "For example, it could be hypothesised that transcripts of deafness-associated genes, MSRB3, ESPN, and WHRN, all in possession of extreme A + U/C + G compositions, are likely to be sensitive to any drug-mediated global dysregulation of expression, with ototoxicity a potential outcome." (PMID 40341320, 2025). "We previously demonstrated that variants in human MSRB3, an MSR family member, are associated with profound autosomal recessive prelingual non-syndromic deafness, DFNB74." (PMID 40827380, 2025). "MSRB3 is within the 137.85-kb QTL interval and functional null mutations of MSRB3 have been associated with deafness in both humans and mouse." (PMID 30587124, 2018). "Supportive evidence for the role of MSRB3 in hearing loss is demonstrated by the enhanced apoptosis in the Change reference 52 to 50 part of the ear and deafness in mice, in which their MSRB3 gene has been disrupted." (PMID 30231496, 2018).
gastric cancer (8 papers, 2020 to 2025). A primary or metastatic malignant neoplasm involving the stomach. "In the present study, we confirmed that high expression levels of MSRB3 were highly associated with peritoneal metastasis and poor prognosis in gastric cancer." (PMID 32226519, 2020). "MSRB3 was a significant risk factor for peritoneal metastasis in gastric cancer patients (peritoneal seed odds ratio OR]:8.467, 95%CI: 2.201-32.576; Ascites Positive OR:7.330, 95%CI: 1.853-29.002)." (PMID 32226519, 2020). "Elevated expression of MSRB3 (methionine sulfoxide reductase), a reactive oxygen species scavenging enzyme, was shown to be associated with poorer survival in gastric cancer." (PMID 33238517, 2020). "Other highly correlated genes that have previously been implicated in gastric cancer included CDH11, MSRB3 and FSTL1." (PMID 35406381, 2022). "It has been reported that high expression levels of MSRB3 in gastric carcinomas can predict peritoneal metastasis, recurrence, and a poor prognosis." (PMID 35804851, 2022). "In vitro experiments confirmed that MSRB3 was a critical protein in regulating gastric cancer cell proliferation and migration." (PMID 32226519, 2020). "In summary, these results demonstrated that MSRB3 was an effective marker for predicting peritoneal metastasis and poor prognosis in gastric cancer." (PMID 32226519, 2020). "The present study was the first to demonstrate that MSRB3 can participate in peritoneal invasion of gastric cancer." (PMID 32226519, 2020). "In the present study, the downregulation of the PI3K/Akt signaling pathway was confirmed in gastric cancer cells by silencing of MSRB3 expression." (PMID 32226519, 2020). "Furthermore, MSRB3 is involved in the regulation of proliferation and migration of gastric carcinoma cells." (PMID 35804851, 2022). "In addition, MSRB3 was also demonstrated as a reliable predictor for metastasis in gastric cancer and prognosis in muscle-invasive BCa." (PMID 34368222, 2021). "Overexpression of MSRB3 is reported in peritoneal metastasis and poor prognosis in gastric cancer." (PMID 34181336, 2021). "In addition, silencing of MSRB3 expression inhibited gastric cancer cell proliferation and migration by downregulating the PI3K/Akt pathway." (PMID 32226519, 2020). "Furthermore, cell validation demonstrated that MSRB3 promoted both proliferation and migration in gastric cancer." (PMID 32226519, 2020). "The expression levels of MSRB3 in different gastric cancer lines were tested by western blotting." (PMID 32226519, 2020). "The regulatory mechanism of gastric cancer metastasis by MSRB3 is unclear." (PMID 32226519, 2020). "In summary, MSRB3 was identified by the WGCNA approach as a critical gene in predicting peritoneal metastasis and recurrence in gastric cancer." (PMID 32226519, 2020).
breast carcinoma (4 papers, 2017 to 2021). "The significant DEGs (CLDN7, BMPER, FGF7, MSRB3) in breast cancer samples compared to normal samples also showed coincident results of significant gene identification." (PMID 34151730, 2021). "Significantly overexpressed genes (CLDN7, MLLT10, RBM33, SH3RF1, SSBP4, and UBE2Z) were correlated with shorter survival, whereas underexpressed genes (BMPER, FGF7, MSRB3, and TNRC6B) were correlated with longer survival in breast cancer." (PMID 34151730, 2021). "The significantly underexpressed genes (BMPER, FGF7, MSRB3, and TNRC6B) in breast cancer were correlated with a longer survival time based on GSE42568 and GSE37751 (P> 0.05), this correlation cannot be demonstrated." (PMID 34151730, 2021). "Upon inhibition of miR-7641 expression, the expressions of several of the target genes (RPS16, RNF4, EMC8, and MSRB3) increased, CUL3 expression decreased, and other genes, including PIGC, remained unchanged in MCF-7 breast cancer cells." (PMID 28827731, 2017). "In addition, MSRB3 further participates in the malignant transformation of normal mammary stem cells in breast cancer 24 and can be used as a predictor of unfavorable survival in muscle-invasive bladder urothelial carcinoma (MIBC) patients." (PMID 32226519, 2020). "Similarly, miR-7641 inhibition in MDA-MB-231 breast cancer cells upregulated RPS16, TNFSF10, MSRB3, CDNF, ZNF616, and NBEA, downregulated CUL3, and showed no remarkable changes for PIGC and the other genes." (PMID 28827731, 2017).
hearing loss (3 papers, 2020 to 2025). "Among the four paralogs (MSRA, MSRB1, MSRB2, MSRB3), so far, only MSRA and MSRB3 have been associated with hearing loss." (PMID 40827380, 2025).
Alzheimer disease (2 papers, 2020 to 2021). A progressive, neurodegenerative disease characterized by loss of function and death of nerve cells in several areas of the brain leading to loss of cognitive function such as memory and language. "MsrB3 expression was seen to change in patients with Alzheimer's disease, and MsrB3 single nucleotide polymorphisms are associated with hippocampal volume." (PMID 32517586, 2020).
Obesity (2 papers, 2020 to 2022). Accumulation of substantial excess body fat. "The study also identified 3 additional genes CLEC7A, MSRB3, and PEX5L that are common among HCL, obesity, and CVD." (PMID 36035865, 2022).
Brachycephaly (1 paper, 2019). An abnormality of skull shape characterized by a decreased anterior-posterior diameter. "A few of these loci, such as CACNA2D3 and MSRB3, have been previously implicated in human reproductive pathologies, whereas others have been associated with domestication-related traits, including brachycephaly (SMOC2) and coat curl (KRT71)." (PMID 31263560, 2019).
colon cancer (1 paper, 2023). "DOK2 and MSRB3’s roles in the colon cancer immune microenvironment and the EMT process require further investigation, making them interesting subjects for future studies." (PMID 37884639, 2023).
deficiencies (1 paper, 2025). "The ABR and DPOAE assessments suggested that the absence of MSRB3 leads to cochlear deficiencies that result in hearing loss." (PMID 40827380, 2025).
peritoneal disease (1 paper, 2020). "Kaplan-Meier survival analysis of peritoneal disease-free survival (pDFS) indicated that high levels of MSRB3 were significantly associated with poor prognosis (log-rank P < 0.001)." (PMID 32226519, 2020). "Survival analysis indicated that high expression levels of MSRB3 were independent predictors of peritoneal disease-free survival (pDFS) as determined by univariate (HR 8.559, 95% CI; 3.339-21.937; P<.001) and multivariate Cox analysis (HR 3.982, 95% CI; 1.509-10.509; P=.005)." (PMID 32226519, 2020).
Stillbirth (1 paper, 2019). Death of the fetus in utero after at least 22 weeks of gestation. "We identified 12 genome-wide significant associations between these traits and genetic loci, including variants near CACNA2D3 with gestation length, MSRB3 and MSANTD1 with litter size, SMOC2 with cesarean section rate and UFM1 with stillbirth rate." (PMID 31263560, 2019).
thyroid cancer (1 paper, 2017). "Thus, variants in MSRB3 could be related with the pathogenesis of thyroid cancer." (PMID 28703219, 2017).
cancer (9 papers, 2014 to 2023). A tumor composed of atypical neoplastic, often pleomorphic cells that invade other tissues. "MSRB3 was reported to promote cancer by regulating genome stability and endoplasmic reticulum stress." (PMID 36930369, 2023). "MSRB3 has been recognized as one of the methionine sulfoxide reductase enzymes and plays an important role in cancer cell apoptosis." (PMID 34368222, 2021). "The depletion of MsrB3 can induce cancer cell apoptosis via adjusting the production of reactive oxygen species (ROS) and the activation of the intrinsic mitochondrial pathway." (PMID 32908641, 2020). "Likewise, MSRB3 knockdown in several other human cancer cell lines reduces cell proliferation while the overexpression of MSRB3 stimulates these cell’s proliferation." (PMID 30231496, 2018). "Furthermore, MSRB3 knockdown induces cancer cell apoptosis through endoplasmic reticulum stress-dependent pathways." (PMID 30231496, 2018). "Interestingly, several cancer genomic databases show that the transcription of both the transcription factor ZEB1 and MSRB3 are correlated in breast cancer." (PMID 30231496, 2018). "As a result, the GO functions for DACT3, TNS1, and MSRB3 included actin binding, actin cytoskeleton, negative regulation of immune system process, and cell adhesion molecule binding, which were well-recognized biological processes for metastasis of cancers." (PMID 34368222, 2021). "However, the function of MSRB3 in cancer metastasis has not been investigated to date." (PMID 32226519, 2020).
tumor (9 papers, 2014 to 2025). "The fusion of MSRB3 was found in the primary and metastasis tumour spindle cells." (PMID 28703219, 2017). "Whereas the HMGA2::MSRB3 and HMGA2::FHIT fusions were described in previous studies, the remaining detected fusion partners such as ARID2 or IFNG-AS1 are novel in this tumor type." (PMID 40033554, 2025). "Interestingly, we also found that a small portion of genes was not consistently expressed in different tumor cell lines, such as GHR and MSRB3." (PMID 35719407, 2022).
cardiovascular disease (1 paper, 2023). "DLEU7 is associated with cardiovascular disease and systolic blood pressure, whereas MSRB3 plays a relevant role in protein and lipid metabolism." (PMID 37328831, 2023).
MSRB3 also shares sentences with these, for which no sentence is quoted: lymph node metastasis (2 papers); Ascites (1); bladder cancer (1); cervical cancer (1); depression (1); infection (1); late-onset Alzheimers disease (1); lung adenocarcinoma (1); mental disorder (1); neurodevelopmental disorder (1).